RNU7-23P (RNA, U7 small nuclear 23 pseudogene)
Synonyms: U7.23
Gene: Small nuclear RNA gene on chromosome 11 (66,919,762 to 66,919,823, forward strand). Ensembl gene ENSG00000239099.
Homologues: Orthologues: macaque U7 (95% identical). Paralogues in human: RNU7-14P (90% identical), RNU7-40P (90% identical), RNU7-7P (90% identical), RNU7-28P (89% identical), RNU7-34P (89% identical), RNU7-35P (89% identical), RNU7-3P (89% identical), RNU7-45P (89% identical), RNU7-11P (87% identical), RNU7-128P (87% identical), RNU7-13P (87% identical), RNU7-143P (87% identical), and 142 more.